MTOR (mechanistic target of rapamycin kinase)
Diseases named in the same sentence as MTOR in open-access papers (continued):
Sharing a sentence is not in itself a finding about the gene and the disease.
endometrial tumors (9 papers, 2012 to 2024). "Studies in mouse models of invasive endometrial tumors show that loss of Lkb1 or concurrent loss of Pten and Lkb1 confer a strong dependence on mTOR signaling for tumor growth, rendering them hypersensitive to mTOR inhibition." (PMID 39544365, 2024). "Up to 93% of so-called Type I endometrial tumors (endometrioid type) are missing the phosphatase and tensin homologue (PTEN), or have mutations in the PI3K/Akt/mTOR pathways that it regulates." (PMID 35439978, 2022). "Basing on the literature indicating mTOR pathway activation in endometrial tumors several mTOR inhibitors have been studied in this cancer." (PMID 22920721, 2012). "The dual inhibition of the PI3K and MAPK pathways might overcome the resistance to PI3K/mTOR inhibition alone in certain endometrial tumors with K-Ras alterations through its enhanced cytostatic effect (at least in part)." (PMID 22662154, 2012). "In addition, invasive endometrial tumor with PTEN (phosphatase and tensin homolog) /LKB1(liver kinase B1)-deficiency displays dysregulated Lkb1/Ampk and phosphatidylinositol 3-kinase (PI3K)/Akt signaling with intensive mTOR signaling." (PMID 33921245, 2021). "Stimulation of the IRs and IGF-IRs has been shown to upregulate proliferation of endometrial tumor cells and inhibit apoptosis through the MAPK and PI3K/Akt/mTOR pathways." (PMID 35439978, 2022). "Immunohistochemical analysis was performed on the endometrial tumors to assess effects of ONC201 on proliferation, angiogenesis, and downstream targets of the mTOR/S6 pathway." (PMID 33557912, 2021).
epilepsy syndrome (9 papers, 2015 to 2024). A syndrome that has a characteristic cluster of clinical features and/or lectroencephalographic (EEG) findings that reflect underlying epileptic activity. "As described, NF1 and TSC are two examples where mutations upstream of the mTOR pathway cause dysregulation and subsequent cellular alterations that correlate clinically with epilepsy syndromes and neurodevelopmental disorders." (PMID 26579319, 2015). "The mammalian target of rapamycin (mTOR) pathway’s excessive activation influences epileptogenesis, impacting neuronal excitability, and synapse formation, with genetic mutations contributing to epilepsy syndromes and the modulation of autophagy playing a role in seizure onset." (PMID 40217521, 2023). "Specifically, future steps will likely interrogate the yet unconfirmed role of ethnicity, as demonstrated in other epilepsy syndromes, and incorporate novel concepts of the chronobiology of the mTOR pathway and epigenetic factors in IS generation." (PMID 30486850, 2018). "Rapamycin, an mTOR inhibitor, had some beneficial effects in mouse models and epilepsy syndromes and may hold promise for therapeutic use in AD." (PMID 38999445, 2024). "Patients with DEPDC5 mutations, associated with mTOR pathway dysregulation, may benefit from targeted treatments such as mTOR inhibitors (e.g., everolimus), which have shown promise in related epilepsy syndromes." (PMID 39767570, 2024). "It is well-known that enhanced IP3K/Akt signaling plays a key role in the development of the epileptogenesis and ictogenesis of various epileptic syndromes via suppression of the tuberous sclerosis complex (TSC) and activation of mammalian target of rapamycin (mTOR) signaling." (PMID 33143372, 2020).
Granuloma (9 papers, 2018 to 2024). A compact, organized collection of mature mononuclear phagocytes, which may be but is not necessarily accompanied by accessory features such as necrosis. "The PI3K/AKT1 pathway has also been implicated in activation of mTOR, which has been associated with granuloma formation." (PMID 39080656, 2024). "Loss of control of this sensing pathway and an abnormal interaction between mTOR and autophagy have been proposed to impair antigen clearance and promote the progression of granuloma and disease chronicity." (PMID 36543347, 2022). "The JAK/STAT and mTOR pathways in particular have been investigated because of their role in granuloma formation." (PMID 32760396, 2020). "Interestingly, deregulation of mTOR signaling, such as prolonged mTORC1 activation, leads to metabolic changes, hyperproliferation of macrophages and granuloma formation, contributing to disease progression in human granulomatous sarcoidosis." (PMID 29381692, 2018). "Finally, we saw upregulation of mTOR in CD14 monocytes; induced overactivity of this pathway was sufficient to generate spontaneous granulomas in a recent mouse model." (PMID 33363531, 2020).
intracerebral hemorrhage (9 papers, 2014 to 2025). A cerebrovascular disorder characterized by bleeding into one or both cerebral hemispheres including the basal ganglia and the cerebral cortex. "For example, CISD2 protects neurons after intracerebral hemorrhage by inhibiting ferroptosis through the AKT/mTOR pathway." (PMID 41261172, 2025). "We used the PI3K/AKT pathway inhibitor LY294002 to verify the underlying mechanism of this effect and confirm whether progesterone can promote axonal growth by activating the PI3K/AKT pathway and increasing mTOR after intracerebral hemorrhage." (PMID 35305084, 2022). "Moreover, the decrease in mTOR levels via miR-144 exacerbates brain damage and enhances pro-inflammatory responses in mouse models of intracerebral hemorrhage, suggesting the miR-144/mTOR pathway as a promising target for intracerebral hemorrhage (ICH) treatment." (PMID 39582602, 2024). "However, the role of mTOR in intracerebral hemorrhage (ICH) remains unexplored." (PMID 24602288, 2014).
male infertility (9 papers, 2019 to 2026). The inability of the male to effect fertilization of an ovum after a specified period of unprotected intercourse. "Adenovirus-mediated upregulation of c-Fos was performed in human follicular granulosa cells from male infertility patients, followed by analysis of mRNA and protein levels of c-Fos, ERα, ERβ, and mTOR." (PMID 40937413, 2025). "The dysregulated PI3K-Akt/mTOR signaling pathway has been reported as the most frequently altered signaling pathway in male infertility, making it one of the most important signaling pathways for therapeutic intervention in male infertility." (PMID 36588705, 2022). "Interestingly, male infertility derived from rapamycin treatment was the first sign of mTOR involvement in male reproduction." (PMID 30986927, 2019). "Therefore, we propose a hypothesis that syna deficiency exacerbates testicular lipid accumulation and apoptosis by suppressing the PI3K/AKT/mTOR and Ca2+ pathway, ultimately leading to spermatogenic dysfunction and male infertility." (PMID 42095086, 2026).
medullary thyroid cancer (9 papers, 2013 to 2025). "In contrast, medullary carcinomas with sporadic RET mutations or with wild-type RET were observed with heterogeneous expression of AKT/mTOR pathway molecules, which suggests the need for further elucidation of alternative activation mechanisms." (PMID 23509459, 2013). "Overactivation of the PI3K/Akt/mTOR pathway plays a vital role in the pathogenesis of medullary thyroid cancer." (PMID 36980552, 2023). "The overactivation of the PI3K/Akt/mTOR pathway plays a significant role in the pathogenesis of medullary thyroid cancer." (PMID 37221474, 2023). "To explore medullary thyroid cancer cell death induced by IMCA implicated in the mTOR signaling, we examined the key proteins expressed in the mTOR pathway." (PMID 29498706, 2018). "Several examples provide evidence to support a role for the activation of the PI3K/AKT/mTOR signaling cascade in medullary thyroid cancer." (PMID 23509459, 2013). "Noteworthy, mTOR inhibitors are currently being used in clinical trials for the treatment of medullary thyroid carcinoma." (PMID 23509459, 2013). "Vandetanib, a FDA-approved medullary thyroid cancer therapy that inhibits EGFR, impairs the HIF-1 pathway by targeting the mTOR–HIF-1α–VEGF signaling axis in breast cancer cells and increases survival in advanced medullary thyroid carcinoma." (PMID 34041023, 2021). "Currently, there are several clinical trials in which patients with radioiodine-refractory differentiated and medullary thyroid carcinomas were recruited to test the efficacy of everolimus (RAD001), a novel inhibitor of mTOR, in combination with other drugs (NCT01625520 and NCT01270321)." (PMID 23509459, 2013).
mental disorder (9 papers, 2012 to 2025). A disease that has its basis in the disruption of mental process. "In this review, we have discussed the mechanisms and causal roles of mTOR hyperactivation in several mental disorders." (PMID 38365306, 2024). "Therefore, we speculate that ELS decreased synaptic plasticity via the inhibition of the mTOR pathway in the hippocampus, which may underlie vulnerability to stress and mental disorders in adulthood." (PMID 33381149, 2020). "Research on RAPTOR in mental disorders has focused on the predictive function of mTOR pathway-related genes in antipsychotic-induced extrapyramidal symptoms (EPS)." (PMID 34348681, 2021). "Few studies have researched MTOR gene expression in patients with mental disorders." (PMID 34348681, 2021). "Interestingly, alterations in mTOR signaling pathway have been described in rodent models used for the study of mental disorders." (PMID 32265715, 2020). "Whereas many questions remain to be answered about the role of the PI3K/AKT/GSK3/mTOR signaling in mental disorders, it is possible that the inhibition of the signaling in specific neuronal populations could be associated with distinct behavioral outcomes." (PMID 23320155, 2012). "In the future, it will be interesting to investigate if mTOR is equally activated by all p110 subunits, or if specific p110 isoforms play more important roles than others, which could aid the development of future therapeutic strategies targeting mental disorders with impairments in mTOR." (PMID 24592210, 2014).
mouth ulcers (9 papers, 2012 to 2023). "It is well-known that both sirolimus and everolimus, i.e., mTOR inhibitors, can cause mouth ulcers." (PMID 38138933, 2023). "Management of mTOR inhibitor-related mouth ulcers relies on minimizing (where possible) trough levels, increasing (or adding) systemic steroids, and applying topical clobetasol." (PMID 38138933, 2023). "Mouth ulcers are most often observed after the onset of mTOR inhibitor treatment and typically improve in most cases afterwards." (PMID 38138933, 2023). "Some AEs, however, were predictable or known effects of mTOR inhibitors, often attributed to downregulation of cellular turnover (eg, amenorrhea, mouth ulcers)." (PMID 28792952, 2017). "We have found a linear relation between the published doses of mTOR inhibitors (in log scale) and oral ulcers appearance." (PMID 27613445, 2016). "Oral ulcer is the best‐studied and most frequent dose‐related adverse event of mTOR inhibitors." (PMID 27613445, 2016).
muscular dystrophy (9 papers, 2014 to 2025). Muscular dystrophy (MD) refers to a group of more than 30 genetic diseases characterized by progressive weakness and degeneration of the skeletal muscles that control movement. "Abnormal age- and muscle-dependent mTOR activation has been observed previously in the skeletal muscle of the mdx mouse, a mild model of dystrophin-deficient muscular dystrophy." (PMID 27257474, 2016). "In the present study, we show that 17–25-week-old (hereafter, “aged”) Fktn-deficient dystroglycanopathy mice with later-stage muscular dystrophy have increased activation of mTOR." (PMID 27257474, 2016). "Current research on Muscular Dystrophies (MD) suggests that its occurrence is closely related to several mechanisms, including gene mutations, dystrophin deficiency, and alterations in the Akt/mTOR/p70S6K signaling pathway." (PMID 41195013, 2025). "Functional deficiency of mTOR-dependent signaling is implicated in muscular dystrophy." (PMID 25221510, 2014). "In addition to skeletal muscle atrophy in aging and Pompe's disease, there are several other functional and genetic muscle wasting phenotypes, for example denervation, disuse atrophy, cancer cachexia, muscular dystrophy, mTOR deficiency, and Dannon's disease to name a few." (PMID 26733885, 2015). "As contradicting results relating to the adaptive changes in PI3-K/Akt/mTOR in muscular dystrophy have been observed, future studies using human patients with muscular dystrophy are required." (PMID 25221510, 2014). "At the protein factor pathway level, some studies suggest that alterations in the skeletal muscle Akt/mTOR/p70S6K signaling pathway activity may also contribute to the development of muscular dystrophies." (PMID 41195013, 2025). "Indeed, previous studies have indicated the therapeutic benefit of engaging cell survival signaling or modulating cellular processes involved in cell size, including protein synthesis (through mTOR) and autophagy in other types of muscular dystrophy." (PMID 27257474, 2016). "Gene therapy or recombinant protein delivery of FST has shown significant efficacy in treating muscle atrophy and muscular dystrophy, and it promotes myocyte proliferation through the activation of the PI3K/Akt/mTOR signaling pathway." (PMID 40504789, 2025).
neuropathy (9 papers, 2014 to 2024). A disorder affecting the nervous system that manifests with pain, tingling, numbness, and/or muscle weakness. "Pmp22 overexpression in CMT1A causes neuropathy by a partial loss of PI3K/Akt/mTOR signaling in Schwann cells, which should be ameliorated by the pharmacologic inhibition of PTEN." (PMID 38383802, 2024). "Blmh loss causes astrogliosis in mice while the loss of histone demethylase Phf8, which controls mTOR signaling, causes neuropathy in mice and humans." (PMID 37718819, 2023). "Indeed, homocysteine metabolites inhibit autophagy, elevate Aβ, and induce neuropathy by impairing Phf8/H4K20me1-dependent epigenetic regulation of mTOR in cystathionine β-synthase-deficient mice." (PMID 37718819, 2023). "No major adverse reactions to ART or immunosuppressants were observed aside from neuropathy with mTOR inhibitor therapy." (PMID 37568163, 2023). "A therapeutic benefit of AMPK activation in trauma-induced neuropathy is related to decreases in mTOR and MAPK signaling in injured nerves." (PMID 24955774, 2014). "In this study, we demonstrated cortico-cortical neural excitation of several ROIs under chronic neuropathy using MEMRI, as well as changes in Mn-enhanced signals of the pain-related cortex area after direct infusion of mTOR inhibitors in the brain." (PMID 33267907, 2020). "However, during the stage of neuropathy, mTOR signaling pathway could be offering an interesting target based on its neuroprotective effects, as depicted in many studies where PI3K/Akt/mTOR signaling activation affords neuroprotection." (PMID 31736682, 2019). "Thus, by interfering in the LKB1/AMPK/mTOR/S6K1 pathway, Metformin seems to be a promising drug in the field of neuro-oncology whereby it can destroy cancerous brain cells and their CSCs, revitalize healthy neurons, and even prevent chemotherapy-induced neuropathy." (PMID 26635517, 2015).
ovarian dysfunction (9 papers, 2018 to 2024). The inability of the ovaries to function. "Therefore, down-regulation of fshr and mTOR signaling pathway in esr1 deficient zebrafish may be relevant to ovarian failure." (PMID 30319547, 2018). "We evaluated changes in the expression of AKT/mTOR signaling pathway genes by real time PCR in the peripheral blood of 74 patients with Premature Ovarian Insufficiency and 56 fertile controls and correlated their expression with FMR1 expression." (PMID 35248053, 2022). "With conventional chemotherapy regimens, cytotoxicity-associated ovarian insufficiency involves PF pool depletion by apoptosis or hyperactivation mechanisms, notably mediated by the ABL/TAp63 and PI3K/Akt/mTOR pathways." (PMID 34299104, 2021). "Our findings in the rapamycin-treated mice carry implications for further development of interventions targeting mTOR for age-related diminished ovarian reserve, primary ovarian insufficiency and fertility preservation." (PMID 29330421, 2018). "On the other hand, by the age of 180 dpf, the IGF system and mTOR signaling pathway were comprehensively down-regulated in esr1 mutant zebrafish, accompanied with ovarian failure." (PMID 30319547, 2018). "Furthermore, when grouped according to ovarian reserve, this effect remained significant only for mTOR and S6K, with higher significance note in patients with Premature Ovarian Insufficiency than in the controls." (PMID 35248053, 2022). "Specifically, allethrin can induce excessive oxidative stress and defective autophagy-related apoptosis, probably through inactivation of the PI3K/AKT/mTOR signaling pathway, and these effects may contribute to ovarian dysfunction and impaired fertility in female offspring." (PMID 35742842, 2022). "In Premature ovarian insufficiency patients, activation of AKT/mTOR signaling pathway is remarkable and putatively pathognomonic." (PMID 35248053, 2022). "Our study confirmed metformin could not only improve body weight and metabolism disorders, but also improve ovarian dysfunction in PCOS mice.In addition, we explored metformin could regulate ferroptosis to improve PCOS via the SIRT3/AMPK/mTOR pathway." (PMID 36755918, 2023).
prostate adenocarcinoma (9 papers, 2011 to 2021). "Typically, for prostate adenocarcinoma, the second most common cancer in men, both PI3K/AKT/mTOR pathway and Ras/MAPK pathways are associated with tumour progression." (PMID 32385236, 2020). "Treatment with 70% ethanol extracts of 228 μg/mL licorice for 24 h in LNCaP prostate adenocarcinoma cells induced autophagy‐related cell death by downregulating the Bcl‐2 protein and inhibiting the mTOR pathway." (PMID 28675698, 2017). "Our aim was then to determine if accessory glands tumours were able to reproduce in Drosophila this specific feature of prostate adenocarcinoma which is the co-deregulation of Ras/MAPK and PI3K/AKT/mTOR pathways." (PMID 32385236, 2020).
pulmonary lymphangioleiomyomatosis (9 papers, 2015 to 2025). "Drugs that inhibit mTOR, such as rapamycin, are Food and Drug Administration (FDA) approved for organ transplant rejection prevention, treatment of certain tumors, pulmonary lymphangioleiomyomatosis, and are applied in drug-eluding stents to prevent restenosis of coronary arteries." (PMID 40177636, 2025).
respiratory infections (9 papers, 2017 to 2024). "Finally, these findings might be relevant for other respiratory infections, including those caused by coronaviruses, where the aerosol delivery of molecules tuning autophagy and mTOR/GSK-3β axis might exert a therapeutic effect." (PMID 33936070, 2021). "AKT1 is associated with viral replication and knockdown of AKT or silencing/inhibition of P13K/Akt/mTOR pathways inhibits the replication of respiratory infections such as influenza A and Middle East respiratory syndrome coronavirus (MERS-CoV)." (PMID 38991709, 2024). "This indicates that perhaps careful regulation of mTOR signaling during respiratory infection is important for limiting potential immunopathology and Tmem development; however, further studies are needed to directly implicate mTOR as a player in lung TRM formation." (PMID 29403499, 2018). "One study suggested the treatment of mTOR inhibitors did not increase the incidence of respiratory infections, with assumption that the incidence rate was constant." (PMID 30107845, 2018).